KIF26B (kinesin family member 26B)
Diseases named in the same sentence as KIF26B in open-access papers (continued):
Sharing a sentence is not in itself a finding about the gene and the disease.
nicotine dependence (1 paper, 2017). Physical and psychological dependence on nicotine. "SNPs annotated to genes previously associated to obesity traits (LINGO2, NELL1) and neurological disorders (schizophrenia (ACSM1, KIF26B, NALCN)), and alcohol and nicotine dependence (LINGO, SH3BP5) were found among Prudent reported dietary pattern score associated-SNPs." (PMID 28644415, 2017).
ovarian serous cystadenocarcinoma (1 paper, 2022). A malignant serous cystic epithelial neoplasm arising from the ovary. "In BRCD, CESC, COAD, LIHC, LUAD, LUSC, OV (ovarian serous cystadenocarcinoma), READ, STAD, and UCEC, the expression of KIF26B was higher than the equivalent normal tissues (P < 0.05)." (PMID 35359341, 2022).
serous ovarian cancer (1 paper, 2026). "Moreover, KIF26B expression was consistently high in chemotherapy-resistant tissues across multiple treatment subgroups, with ROC curve analyses confirming its predictive power for chemoresistance, particularly in advanced serous ovarian cancer." (PMID 41751488, 2026).
spinocerebellar ataxia (1 paper, 2018). "Recently, a human missense mutation (D1904N) in KIF26B was found to cause spinocerebellar ataxia, a progressive neurodegenerative disorder, in a patient cohort." (PMID 29621187, 2018). "Importantly, disruption of the domain by a human KIF26B missense mutation recently identified in patients with spinocerebellar ataxia impaired WNT5A-dependent degradation of KIF26B." (PMID 29621187, 2018).
tumor (19 papers, 2012 to 2025). "A study in NSCLC found that KIF26B expression was higher in tumours compared to normal tissues and was associated with poor overall survival of patients." (PMID 40002279, 2025). "Kaplan-Meier analysis with a log rank test for OS was performed to assess the possible association between tumor expression of KIF26B or Ki67 and patient survival." (PMID 25652119, 2015). "Furthermore, recent studies have shown that high expression of KIF26B is associated with malignant expression and drug resistance in tumor cells." (PMID 35866054, 2022). "Moreover, the overexpression of KIF26B in these cancers has been relatively correlated with larger tumor size, higher risk of metastases, and poor prognosis." (PMID 35359341, 2022). "These three methylation sites could regulate the expression of corresponding genes (RUNDC3A, GRIK2, and KIF26B) that cause tumor growth and development, and therefore these sites might become new targets for tumor treatment." (PMID 35669882, 2022). "Ginsenoside Rh2 has tumor-suppressive activity and downregulates the mRNA levels of Kinesin family member 26B (KIF26B), a kinesin motor protein." (PMID 39833727, 2025). "Although the fact that KIF26B mediated tumor promotion has been validated in multiple human cancers, little is known about its impact on HCC." (PMID 38433242, 2024). "On the contrary, we found the KIF26B protein phosphorylation level was higher in tumor tissues compared to normal tissues, while different tumors shared diverse phosphorylation sites." (PMID 35359341, 2022). "KIF26B is a downstream target of the zinc finger protein Sall1, which is involved in the development of various tumours." (PMID 35292033, 2022). "The finding that the KIF26B gene has a universal high expression across various tumor tissues suggests the importance of a pan-cancer analysis." (PMID 35359341, 2022). "We also found that the expression of KIF26B was closely related to KI67, a clinically recognized marker of tumor proliferation, indicating that KIF26B is closely related to tumor growth." (PMID 35866054, 2022). "The phosphorylation levels of the KIF26B protein between tumor samples and normal tissues were compared." (PMID 35359341, 2022). "There was a negative correlation between the abundance of F. nucleatum and METTL3 levels in CRC tumor tissues, as well as a negative correlation between the expression levels of METTL3 and KIF26B in CRC tumor tissues." (PMID 35273176, 2022). "Our analysis revealed that the gene expression of KIF26B was significantly higher in 23 types of tumor tissues than in adjacent normal tissues." (PMID 35359341, 2022). "Based on the open databases TCGA, TIMER2, GEPIA2, GTEx, CPTAC, and HPA, we found that, when compared with normal tissues, KIF26B is overexpressed in 22 tumor tissues." (PMID 35359341, 2022). "The results showed that expression of KIF26B was higher in HCC patients and increases with tumor TNM stage, overexpression of KIF26B was associated with poor differentiation." (PMID 31388332, 2019). "Then, we detected expression of Ki67 in nude mouse tumor tissue by IHC, and found that expression of Ki67 was significantly decreased under condition of KIF26B knockdown." (PMID 31388332, 2019). "To further demonstrate function of KIF26B in vivo, we constructed KIF26B knockdown stable cell line and conducted subcutaneous tumor formation in nude mice." (PMID 31388332, 2019). "Recently, miR-20a-5p was shown to suppress Dox chemoresistance of OS in tumor xenografts of nude mice via its repression of its target gene KIF26B." (PMID 29118673, 2017). "In our study, we found that high KIF26B expression correlated positively with Ki67 expression, suggesting that KIF26B is involved in tumor cell proliferation." (PMID 25652119, 2015). "The mean KIF26B mRNA expression was significantly higher in the 40 tumor tissue specimens compared with that in the paired adjacent normal mucosa specimens (4.35 ± 1.33 vs. 2.06 ± 0.86, respectively; P < 0.01, Student’s t-test)." (PMID 25652119, 2015).
tumor (continued). "Upregulated KIF26B expression was significantly correlated with tumor size (P = 0.020), AJCC stage (P = 0.018), T stage (P = 0.026), N stage (P = 0.013), and histological differentiation (P = 0.047)." (PMID 25652119, 2015). "Immunohistochemistry revealed that KIF26B expression significantly correlated with clinicopathological factors, including tumor size (P = 0.011), grade (P = 0.017), lymph node status (P = 0.009) and ER status (P = 0.012)." (PMID 23585914, 2013). "Significant correlations were found between KIF26B expression and four clinicopathological factors including tumor size (P = 0.011), lymph node status (P = 0.009), grade (P = 0.0017), and ER status (P = 0.012)." (PMID 23585914, 2013). "KIF26B silencing in H1299 and H520 cell lines slowed proliferation, impaired invasion, induced cell cycle arrest in vitro, and suppressed the growth of H520 tumour xenografts in mice." (PMID 40002279, 2025). "Interestingly but notably, two members (KIF26A and KIF26B) of this subfamily have opposing effects on tumor progression." (PMID 38433242, 2024). "Kinesin-11 family: KIF26A and KIF26B appear to have opposing roles in tumor progression." (PMID 38433242, 2024). "KIF26B facilitated tumor development via the PI3K/Akt/mTOR signaling pathway and could be negatively regulated by miR-450b-5p." (PMID 38433242, 2024). "Then, we analyzed the expression ratio of KIF26B in each tumor sample and normal samples." (PMID 35866054, 2022). "Interestingly, the expression levels of METTL3 were downregulated in tumor tissues, while the KIF26B levels were significantly higher in tumor tissues than in matched non-tumor tissue." (PMID 35273176, 2022). "Suppression of KIF26B could inhibit cell viability, proliferation rate, invasion ability and tumor formation ability of HCC cells, and such phenomenon might be correlated with inhibition of PI3K/AKT signaling pathway." (PMID 31388332, 2019). "Furthermore, upregulated expression of KIF26B was significantly correlated with tumor size (P = 0.020), American Joint Committee on Cancer (AJCC) stage (P = 0.018), T stage (P = 0.026), N stage (P = 0.013), and differentiation histology (P = 0.047)." (PMID 25652119, 2015). "Western blot analysis also showed that KIF26B protein expression was significantly higher in the 40 tumor tissue specimens compared with that in the paired adjacent normal mucosa specimens (2.33 ± 0.07 vs. 0.91 ± 0.04, respectively; P < 0.01, Student’s t-test)." (PMID 25652119, 2015). "Using a univariate analysis in the Cox proportional hazards model, a decreased OS was associated with the following characteristics: tumor location, tumor depth, AJCC stage, LNM stage, distant metastasis, vascular invasion and the expression of KIF26B and Ki67." (PMID 25652119, 2015). "Tumor showed variable KIF26B expression: weak, moderate, and strong." (PMID 23585914, 2013). "Furthermore, KIF26B expression and those clinicopathologic variables significant in univariate analysis (i.e., tumor size, lymph node status, clinical stage, grade, ER, and KIF26B) were further evaluated in multivariate analysis." (PMID 23585914, 2013). "However, when comparing tumor versus transgenic tissue gene Kif26b showed a change in direction and when comparing tumor versus non-transgenic tissue the genes Mthfd1, Myom1 and Ppp2r5c equally differed in direction of gene expression." (PMID 22815814, 2012). "When comparing tumor versus transgenic tissue the gene Kif26b showed change in direction." (PMID 22815814, 2012). "With the IHC measurement of KIF26B in HCC tissue microarrays (TMA) consisting of 93 paired tumor and peritumoral samples, it was observed that the expression of KIF26B was elevated and positively correlated with advanced tumor stage and grade, which could also indicate a shorter OS for HCC patients." (PMID 38433242, 2024). "We further explored whether KIF26B was differentially expressed in tumor and normal tissues." (PMID 35359341, 2022).
tumor (continued). "To investigate whether overexpression of KIF26B could reverse tumor suppressive effect of miR-450b-5p in HCC cells, we constructed KIF26B overexpression plasmid and observed that such plasmid could almost reverse KIF26B suppression effect of miR-450b-5p in HCC cells." (PMID 31388332, 2019). "In addition, we found that suppression of KIF26B could inhibit the tumor formation ability of HCC cells in vitro." (PMID 31388332, 2019). "The results showed that miR-450b-5p could significantly inhibit cell viability, proliferation rate, cell invasion ability and colony formation ability of HCC cells, while KIF26B overexpression plasmid could partially reverse the tumor suppressive effect of miR-450b-5p in HCC cells." (PMID 31388332, 2019). "Furthermore, we observed that miR-450b-5p could obviously inhibit cell viability, proliferation rate, invasion ability and tumor formation ability of HCC cells, while overexpression KIF26B could partially reverse tumor suppression function of miR-450b-5p." (PMID 31388332, 2019). "Thus, we proved that suppression of KIF26B could inhibit proliferation, invasion and tumor formation ability of HCC cells through regulating activation of PI3K/AKT signaling pathway." (PMID 31388332, 2019). "Thus, we demonstrated that suppression of KIF26B could affect tumor formation ability of HCC cells in vivo." (PMID 31388332, 2019). "Thus, our study demonstrated that overexpression of KIF26B could partially reverse tumor suppressive effect of miR-450b-5p in HCC cells." (PMID 31388332, 2019). "In addition, we find that high KIF26B expression positively correlated with ER status, which suggested KIF26B may induce tumor proliferation." (PMID 23585914, 2013). "In this work, we summarized the molecular features of the KIF26B gene in 33 different tumors through the TCGA, GEO, and CPTAC databases and predicted the functional mechanism of tumor occurrence and development." (PMID 35359341, 2022). "Protein staining for biomarkers related to EC (CECR1, KIF26B, PIK3CA) was mainly localized to the cytoplasm of tumor cells." (PMID 32133296, 2020). "In univariate analysis, larger tumour size, with pharmaceutical drug adjuvant therapy, high FNCLCC grade, increased COL11A1, ITGA10 and KIF26B expression, and decreased CLEC3B, DUOX2, KRT75 and PPP2R2B were risk factors of shorter RFS." (PMID 31742892, 2020). "In this study, we found KIF26B was overexpressed in HCC tissues, high expression of KIF26B was correlated with later TNM stage, poor tumor differentiation and prognosis." (PMID 31388332, 2019). "Using quantitative real-time PCR and Western blot analyses as well as immunohistochemical staining of a tissue microarray we examined KIF26B mRNA and protein levels in CRC tumor tissues and paired adjacent normal mucosa." (PMID 25652119, 2015). "Taken together, our data indicate that KIF26B plays an important role in CRC carcinogenesis, especially in tumor development, progression and proliferation." (PMID 25652119, 2015). "Suppression of KIF26B could inhibit proliferation rate and invasion ability of HCC cells in vitro, and affect tumor formation ability both in vitro and in vivo." (PMID 31388332, 2019).
cancer (14 papers, 2013 to 2026). A tumor composed of atypical neoplastic, often pleomorphic cells that invade other tissues. "The inhibition of METTL3 resulted in decreased m6A methylation of KIF26B mRNA, a gene associated with cell-cell adhesion and important for cancer cell invasion." (PMID 38023192, 2023). "In conclusion, this pan-cancer analysis found that KIF26B can act as an oncogene and can have genetic alterations associated with the diagnosis and prognosis of various cancers." (PMID 35359341, 2022). "Previous studies have suggested that high expression of KIF26B is an indicator of poor prognosis in various cancers." (PMID 35359341, 2022). "Correlations between prognosis and KIF26B gene expression in various cancers were studied using the GEPIA dataset." (PMID 35359341, 2022). "The relationship between KIF26B expression and pathological stages of cancers was analyzed via the “Stage Plot” component of GEPIA, and strong positive correlations were found for BLCA, KICH, LIHC, and PAAD (P < 0.05)." (PMID 35359341, 2022). "Recent studies have found that KIF26B gene contributes to tumorigenesis and endows certain cancers with malignant behavior." (PMID 35866054, 2022). "This study illustrates the function of KIF26B from a pan-cancer perspective and offers a new horizon for cancer prognostic and immunotherapeutic investigations." (PMID 35359341, 2022). "Following a survival analysis, a relationship between the expression of KIF26B and the prognosis of various cancers was observed." (PMID 35359341, 2022). "Here, we first examined how KIF26B intervenes in thirty-three cancers within the TCGA database, including potential immunological functions, and how it affects the prognosis." (PMID 35359341, 2022). "This study evidenced that the expression of KIF26B and the immune infiltration of endothelial cells were positively correlated in most cancers, except for COAD, SKCM, and SKCM-metastasis." (PMID 35359341, 2022). "Independent validation of these clinical findings, examination of KIF26B expression in other kinds of cancers, and further investigation of the cell biology of KIF26B and its potential as a therapeutic target are clearly warranted." (PMID 23585914, 2013). "KIF26B is relevant to cell proliferation, migration, invasion, and even drug resistance in cancer." (PMID 35359341, 2022). "Furthermore, potential correlations between genetic alterations of KIF26B and clinical prognosis in different cancers were tested." (PMID 35359341, 2022). "Therefore, a possible association between the grade of immune infiltration and the gene expression of KIF26B in various cancer types was investigated." (PMID 35359341, 2022). "This study may contribute to better understanding the role of KIF26B in cancerogenesis and development and provide a new horizon for more precise and personalized treatments for cancers." (PMID 35359341, 2022). "Cancer cases were categorized into low and high-KIF26B expression groups." (PMID 35359341, 2022). "The development of the gene-editing technology in the near future would allow the modification of the KIF26B gene, which could be a promising method for curing cancers such as UCEC, BRCA, SKCM, UCS, LIHC, and STAD." (PMID 35359341, 2022). "We also found positive or negative correlations between KIF26B and the immune infiltration of endothelial cells and cancer-associated fibroblast infiltration." (PMID 35359341, 2022). "In this context, a pan-cancer investigation of KIF26B through various cancers seems necessary." (PMID 35359341, 2022). "In this study, we analyzed genetic alterations of KIF26B in cancers within the TCGA cohorts." (PMID 35359341, 2022). "We hypothesized that knockdown of KIF26B will reduce cancer cell proliferation and is therefore, a potential therapeutic target." (PMID 25652119, 2015). "Moreover, KIF26B can affect endothelial cells' infiltrating and molecular pathways in most cancers." (PMID 35359341, 2022).
cancer (continued). "However, the role of KIF26A, a homologous family member of KIF26B, in cancer remains unknown." (PMID 33505901, 2020). "KIF26B has been identified as an oncogene in several tumors; however, its utility as a prognostic indicator for various cancers has not yet been comprehensively evaluated." (PMID 35359341, 2022). "So far, there was only one research demonstrated that KIF26B participated in PI3K/Akt signaling regulation in HCC, silencing of KIF26B inhibited PI3K/Akt activation by reducing expression of mTOR, p-PI3K, and p-Akt, thereby suppressing the malignant properties of cancer cells." (PMID 38433242, 2024). "Therefore, F. nucleatum could induce epigenetic modifications in the KIF26B gene at transcriptional level through the YAP/FOXD3/METTL3 axis, ultimately facilitating the invasiveness of cancer cells." (PMID 38023192, 2023).
neurodevelopmental disorder (1 paper, 2026). A behavioral and cognitive disorder with onset during the developmental period that involves impaired or aberrant development of intellectual, motor, or social functions. "Kif26a and Kif26b encode a family of unconventional kinesins with emerging roles in neurodevelopment, and mutations in both genes have been implicated in a spectrum of neurodevelopmental disorders." (PMID 42239235, 2026).
psychiatric disorder (1 paper, 2018). A disorder characterized by behavioral and/or psychological abnormalities, often accompanied by physical symptoms. "We detected two missense somatic mutations in KIF26B and NAV, both of which are expressed in neurons, in the co-twin with no psychiatric disorder (TT12)." (PMID 29654278, 2018).
KIF26B also shares sentences with these, for which no sentence is quoted: neurological disorders (2 papers); Aphasia (1); Autoimmunity (1); epilepsy (1); gout (1); keratoconus (1); liver cancer (1); lymph node metastasis (1); multicystic dysplastic kidney (1); Obesity (1); rectal cancer (1); renal coloboma syndrome (1); schizophrenia (1); self-limited familial infantile epilepsy (1); thymoma (1); triple-negative breast carcinoma (1); uterine carcinosarcoma (1); vesicoureteral reflux (1).